MIR515-2 (microRNA 515-2)
Synonyms: hsa-mir-515-2; MIRN515-2
Gene: MicroRNA gene on chromosome 19 (53,685,009 to 53,685,091, forward strand). Ensembl gene ENSG00000207615.
Gene Ontology:
Biological process: miRNA-mediated post-transcriptional gene silencing
Homologues: Orthologues: chimpanzee ptr-mir-515-1 (100% identical), macaque mml-mir-519e (90% identical). Paralogues in human: MIR515-1 (100% identical), MIR518D (81% identical), MIR520C (81% identical), MIR519A2 (80% identical), MIR520E (80% identical), MIR518C (78% identical), MIR516A1 (76% identical), MIR517A (76% identical), MIR524 (76% identical), MIR516A2 (75% identical), MIR519C (75% identical), MIR520F (75% identical), and 12 more.